TYROBP (transmembrane immune signaling adaptor TYROBP)
Diseases named in the same sentence as TYROBP in open-access papers (continued):
Sharing a sentence is not in itself a finding about the gene and the disease.
cancer (35 papers, 2018 to 2025). A tumor composed of atypical neoplastic, often pleomorphic cells that invade other tissues. "Across multiple cancer studies, the TYROBP network was always positively-associated with immune infiltration, such as the increased infiltration of CD8+ T cells, DCs, and macrophages." (PMID 35078433, 2022). "In conclusion, TYROBP is tightly associated with cancer progression." (PMID 38549127, 2024). "Furthermore, the transcriptional levels of FCER1G and SPI1 can also distinguish the OS patients into two clusters with different prognosis and immune cell infiltrations, suggesting a potential treatment target for OS and other TYROBP-associated cancers." (PMID 35078433, 2022). "Besides, several researches have indicated the association of TYROBP and macrophage polarization in cancers through bioinformatics analysis." (PMID 36466903, 2022). "It has recently been reported that cell fusion contributes to the spread of cancer, and TYROBP is critical for the fusion of macrophages." (PMID 36595751, 2022). "Firstly, we found that the expressional level of TYROBP was significantly (adjusted p < 0.05) lower in cancers including READ, PAAD, LUAD, LUSC, COAD, and OS, while the expressional level was higher in cancers including THCA, BRCA, STAD, ESCA, and GBM." (PMID 35078433, 2022). "By overlapping the 80 of down-regulated co-expression genes and 109 up-regulated co-expression genes, we got 54 of conversed TYROBP co-expressed genes (R > 0.6 and p < 0.05) across multiple cancer types." (PMID 35078433, 2022). "Reports state that TYROBP, TLR4, and ITGAM are involved in several cancer-immune microenvironment-associated pathogeneses, including OS23." (PMID 34588497, 2021). "TYROBP is mainly involved in immune signaling pathways, but an increasing number of studies have shown that TYROBP can be used as a prognostic marker for cancer." (PMID 34195091, 2021). "It has recently been reported that cell fusion contributes to cancer spreading, and TYROBP is essential for macrophage fusion." (PMID 33015999, 2020). "In addition, TYROBP was probably related to pathological development of MM via cancer-related signaling pathways, such as cell adhesion molecule signaling." (PMID 38549127, 2024). "Studies have shown that the TYROBP gene may play a role in the development and progression of certain cancers." (PMID 37207157, 2023). "To furtherly explore the function of TYROBP-centered top 1 cluster, we did an analysis across cancer types to identify a more conserved and extensive TYROBP co-expression network, which was found to be significantly associated with leukocyte proliferation and T cell activation later." (PMID 35078433, 2022). "Although the exact mechanisms by which TYROBP contributes to tumorigenesis are not yet fully understood, these findings suggest that TYROBP may be a potential target for cancer therapy and highlight the need for further research into its role in cancer development and progression." (PMID 37207157, 2023). "There were also significant interactions between insulin-expressing cancer cells and immune cells, namely CD40LG (INS+FOSlow, INS+) − CD40 (B cell) and APP (INS+) − TREM2 + TYROBP (macrophage)." (PMID 40438247, 2025). "In myeloid cells, the top 50 pan-cancer central genes included seven genes involved in myeloid cell differentiation (CD4, FCER1G, IRF8, TYROBP, TLR2, TREM2 and ITGAM), but only two of them (FCER1G and TYROBP) were found among the top 50 DEGs." (PMID 36350625, 2023). "Through further analysis, we found that TYROBP, FCGR2B, TYROBP, LY86, and TLR2 genes were highly expressed in ccRCC carcinoma tissues." (PMID 36595751, 2022). "Previous studies have demonstrated that TYROBP, also known as DAP12, is overexpressed in various cancers." (PMID 34336848, 2021). "In addition, we predicted the sensitivity of common anti-cancer drugs on prognostic signature, including CCR5, HMOX1, CTSC, CD5, BCL3, CDH1, TYROBP and CD38." (PMID 38767825, 2024).
cancer (continued). "We explored them utilizing the pathway activity module of the GSCALite platform to determine whether these six genes (TYROBP, FCER1G, CD48, LST1, APOE, and APOC1) act through specific cancer pathways." (PMID 38515073, 2024). "Similarly, we revealed that TERC promotes cellular inflammatory response by upregulating the expression of immune-related genes such as LIN37, TPRG1L, TYROBP and USP16 in human normal and cancer cells." (PMID 31294790, 2019).
neurodegenerative disease (22 papers, 2013 to 2025). A disorder of the central nervous system characterized by gradual and progressive loss of neural tissue and neurologic function. "Despite the close functional connection between TREM2 and DAP12, the potential contribution of TYROBP variants to neurodegenerative diseases remain inconclusive." (PMID 40301889, 2025). "However, whether deficiency of TYROBP contributes to, or protects against neurodegenerative disease, remains controversial." (PMID 35386591, 2022). "Overall, a better understanding of TYROBP and its many interactors and pathways will improve our understanding of the role(s) played by microglia in the etiology and pathogenesis of human neurodegenerative diseases." (PMID 36002854, 2022). "This type of response is observed in other neurodegenerative diseases where homeostatic functions of microglia are suppressed by inhibition of TYROBP signalling." (PMID 32450896, 2020). "The lack of an increase in GFAP in the absence of TYROBP led us to specifically interrogate other astrocytic markers often associated with neurodegenerative disease and neuroinflammation, i.e., “neurotoxic reactive astrocytes”." (PMID 38459557, 2024). "High correlation results are also observed in two other neurodegenerative disease involving TYROBP." (PMID 23662159, 2013).
infection (18 papers, 2011 to 2025). The state of being infected such as from the introduction of a foreign agent such as serum, vaccine, antigenic substance or organism. "For example, TYROBP, CCR7, CXCL10, and CXCL11 emerged as top DEGs in both infected and bystander cells in ADE compared to conventional infection." (PMID 39902963, 2025). "The expression level of several proinflammatory genes including TYROBP, S100A8, S100A11, LBP and CD88 were increased significantly after infection." (PMID 39398025, 2024). "The DEG analysis showed that LAIR2, CD7, KLRB1, TYROBP, TRAV19, TRAV21, and TRBV6-5 were upregulated in group E VS group B both breakthrough infection by BA.5.2." (PMID 39835127, 2024).
bone cysts (14 papers, 2015 to 2025). "In addition, we present the first reported case of a monoallelic TYROBP deletion carrier with NHD-type bone cysts." (PMID 40301889, 2025). "We report here a case of a monoallelic 5.2-kb TYROBP deletion carrier with classic painful NHD bone cysts but no detectable brain pathology, cognitive findings, or neuropsychiatric symptoms at age 34 years." (PMID 40301889, 2025).
immune disease (3 papers, 2021 to 2023). "One case report describes NHD patients harboring TYROBP mutations exhibits decreased number of NK cells and immune dysfunction, similar to phenotypes of Tyrobp KO mice, suggesting NK cells may be involved in DAP12-mediated cognitive alterations in dementia." (PMID 38031097, 2023).
psychiatric diseases (1 paper, 2015). "Further studies of the TREM2/TYROBP signaling should be performed to elucidate its role in neurological and psychiatric diseases." (PMID 26332043, 2015).
vasculopathy (1 paper, 2022). "In addition, our results revealed the microvascular profile that favors the disease phenotype of microglial mirrored in the upregulation of TYROBP, TREM2, and Cst7 in both early and late stages of CAA vasculopathy." (PMID 35813502, 2022).
TYROBP also shares sentences with these, for which no sentence is quoted: osteopetrosis (10 papers); frontotemporal dementia (6); rheumatoid arthritis (6); viral infections (5); amyotrophic lateral sclerosis (4); lung carcinoma (4); bacterial infection (3); glioblastoma (3); kidney disease (3); lupus nephritis (3); osteoarthritis (3); renal carcinoma (3); acute lymphoblastic leukemia (2); Arthritis (2); asthma (2); autism (2); cardiovascular diseases (2); Cerebral atrophy (2); colorectal cancer (2); cytomegalovirus infection (2); infectious disease (2); liver cancer (2); lymphoma (2); metastasis (2); metastatic colorectal cancer (2); neurological diseases (2); peripheral nerve injury (2); prostate carcinoma (2); renal fibrosis (2); sarcoma (2).
A further 56 diseases each share a sentence with TYROBP in 1 paper.